FBXL14 (F-box and leucine rich repeat protein 14)
Description:
Substrate-recognition component of some SCF (SKP1-CUL1-F-box protein)-type E3 ubiquitin-protein ligase complexes. The SCF(FBXL14) complex acts by mediating ubiquitination and subsequent degradation of SNAI1.
Synonyms: FBL14; MGC40195
Tractability: No criterion of Open Targets' tractability assessment is met for any kind of drug.
Gene: Protein-coding gene on chromosome 12 (1,565,993 to 1,594,581, reverse strand). Ensembl gene ENSG00000171823.
Subcellular location: Cytoplasm
Pathways (Reactome):
Immune System: Antigen processing: Ubiquitination & Proteasome degradation
Metabolism of proteins: Neddylation
Gene Ontology:
Molecular function: protein binding; ubiquitin-protein transferase activity
Biological process: ubiquitin-dependent protein catabolic process; regulation of DNA-templated transcription; SCF-dependent proteasomal ubiquitin-dependent protein catabolic process
Cellular component: cytoplasm; cytosol
Genetic constraint (gnomAD): Loss-of-function variants: 10 observed, 22.9 expected, observed/expected ratio (o/e) 0.44, 90% interval 0.27 to 0.74. The upper end of that interval is the gene's LOEUF score, 0.74, which puts it in group 3 of 6, group 1 being the genes least tolerant of losing a copy. Missense variants: 368 observed, 539.81 expected, observed/expected ratio (o/e) 0.68, 90% interval 0.62 to 0.74. Synonymous variants: 285 observed, 237.48 expected, observed/expected ratio (o/e) 1.2, 90% interval 1.09 to 1.32.
Homologues: Orthologues: chimpanzee FBXL14 (100% identical), guinea pig FBXL14 (99% identical), dog FBXL14 (96% identical), macaque FBXL14 (96% identical), mouse Fbxl14 (95% identical), rabbit FBXL14 (95% identical), rat Fbxl14 (92% identical), tropical clawed frog fbxl14 (90% identical), zebrafish fbxl14b (88% identical), zebrafish fbxl14a (84% identical), Drosophila melanogaster Ppa (59% identical), Caenorhabditis elegans gadr-5 (17% identical), and 14 more. Paralogues in human: FBXL13 (23% identical), FBXL7 (22% identical), FBXL2 (22% identical), FBXL20 (21% identical), FBXL16 (18% identical), FBXL5 (17% identical), FBXL4 (16% identical), FBXL18 (15% identical), FBXL6 (15% identical), SKP2 (15% identical), FBXL17 (14% identical), FBXL19 (14% identical), and 3 more.
Diseases named in the same sentence as FBXL14 in open-access papers:
FBXL14 is named in the same sentence as 19 diseases in open-access papers, as found by Europe PMC text mining. Sharing a sentence is not in itself a finding about the gene and the disease. The quoted sentences say what the papers report.
gastric cancer (4 papers, 2021 to 2023). A primary or metastatic malignant neoplasm involving the stomach. "BRD4 binds with Snail on acetylated lysine K146 and K187 to inhibit Snail degradation by its E3 ubiquitin ligases FBXL14 and β-TrCP1, thereby maintaining progression and metastasis in gastric cancer." (PMID 37737256, 2023). "FBXL5 and FBXL14 also act as tumor suppressor genes in gastric cancer, cervical cancer, and head and neck cancer through degrading Snail1 and inhibiting EMT." (PMID 34249081, 2021).
glioma (4 papers, 2019 to 2025). A benign or malignant brain and spinal cord tumor that arises from glial cells (astrocytes, oligodendrocytes, ependymal cells). "The phosphorylation of USP13 at Tyrosine 708 by CLK3 is required for USP13′s binding to c-Myc, which prevents its Fbxl14-mediated ubiquitination of c-Myc in glioma stem cells." (PMID 36612196, 2022). "Overexpression of FBXL14 induces the differentiation of and inhibits tumor formation by glioma stem cells, with these effects being reversed by expression of the c-Myc(T58A) mutant." (PMID 32429232, 2020). "In line with this, the deubiquitinase USP13 is highly expressed in glioma stem cells, where it stabilizes c-Myc by antagonizing FBXL14-mediated ubiquitination; this in turn enhances stem cell self-renewal and tumor growth." (PMID 30999935, 2019). "FBXL14 overexpression induces the degradation of c-Myc, promotes glioma stem cell differentiation, and represses tumor growth." (PMID 30999935, 2019). "FBXL14 is preferentially expressed in non-stem- like glioma cells and neural progenitors, whereas it is expressed at only a low level in glioma stem cells that contribute to tumor initiation and malignant progression." (PMID 32429232, 2020).
breast carcinoma (3 papers, 2021 to 2023). "It was also noted that ectopic expression of FBXL14 reduced vimentin level in breast cancer cells." (PMID 33801272, 2021).
cholangiocarcinoma (2 papers, 2021 to 2022). A carcinoma that arises from the intrahepatic biliary tree (intrahepatic cholangiocarcinoma) or from the junction, or adjacent to the junction, of the right and left hepatic ducts (hilar cholangiocarcinoma). "In research on nucleotide anabolism in cholangiocarcinoma, CDC like kinase 3 (CLK3) was found to activate the rate-limiting enzyme in de novo purine anabolism, ATIC, by regulating the USP13/Fbxl14/c-Myc signaling axis, thereby promoting the molecular progression of cholangiocarcinoma." (PMID 33952722, 2021).
head and neck cancer (2 papers, 2019 to 2021). A primary or metastatic malignant neoplasm affecting the head and neck. "In summary, SKP2 enhances EMT in breast cancer and melanoma, whereas FBXL5 suppresses EMT in human gastric and cervical cancer cells, and FBXL14 is an EMT inhibitor in head and neck cancer cells." (PMID 30999935, 2019). "Consistently, one group revealed that imipramine blue inhibited head and neck cancer cell invasiveness by enhancing FBXL14-triggered Twist degradation, which indicates that FBXL14 could function as an EMT inhibitor to suppress metastasis in human cancers." (PMID 30999935, 2019).
chronic myelogenous leukemia (1 paper, 2022). "To further investigate this, we next undertook analyses in HAP1 chronic myelogenous leukemia cells with a complete CRISPR–Cas9 KO of FBXL14." (PMID 36372232, 2022).
melanoma (1 paper, 2022). A malignant, usually aggressive tumor composed of atypical, neoplastic melanocytes. "These experiments were performed in A375 melanoma cells, whereas FBXL14 was stably knocked down or overexpressed." (PMID 36372232, 2022). "However, we consistently observed that FBXL14 overexpression, which enhanced RPA194 degradation, sensitized the A375 melanoma cells to loss of viability and growth by BMH-21 as measured by a decrease in the GI50 and a reduction in the number of surviving colonies upon BMH-21 treatment." (PMID 36372232, 2022). "Furthermore, FBXL14 overexpression sensitized A375 melanoma cells to BMH-21-mediated cell death." (PMID 36372232, 2022). "To do this, we used an FBXL14 shRNA lentiviral vector to generate stable A375 melanoma and U2OS osteosarcoma cells with effective KD of FBXL14." (PMID 36372232, 2022).
metastasis (1 paper, 2021). The spread or migration of cancer cells from one part of the body (where they first appeared) to another. "This study highlights the potential of vimentin-FBXL14 complexes as a therapeutic strategy to target EMT-induced metastasis disease, and the targeting vimentin by IGFBP-3 contributing to our understanding of the better means to control cancer metastasis." (PMID 33801272, 2021).
cancer (6 papers, 2019 to 2024). A tumor composed of atypical neoplastic, often pleomorphic cells that invade other tissues. "This was demonstrated by the strict dependency of the inducible RPA194 turnover on FBXL14 in cancer cell lines and the ability of FBXL14 expression to affect RPA194 ubiquitination." (PMID 36372232, 2022). "We also showed that FBXL14 overexpression activated RPA1 turnover in cancer cell lines that were resistant to this degradation." (PMID 36497261, 2022). "Expression of FBXL14 also led to the BMH-21-mediated degradation of RPA194 in two cancer cell lines refractory to this effect." (PMID 36372232, 2022). "FBXL14 gene expression mediates the epithelial–mesenchymal transition (EMT) in cancer, which indicates that FBXL14 could function as an EMT inhibitor to suppress metastasis in human cancers." (PMID 36109686, 2023). "Taken together, these results suggested that IGFBP-3 internalizes and makes a complex formation with vimentin and FBXL14, thereby causing polyubiquitination and proteasomal degradation of vimentin and suppressing EMT-associated metastatic phenotypes of cancer cells." (PMID 33801272, 2021). "Our findings reveal the inhibitory effect of IGFBP-3 on cancer migration and metastasis by negatively regulating vimentin expression through ubiquitin-mediated proteasome degradation through the cooperation with the E3 ligase FBXL14 in aerodigestive tract cancer cells." (PMID 33801272, 2021). "Therefore, FBXL14 appears to be a common regulator of the EMT program and targeting FBXL14 may control the EMT-mediated metastatic process in cancer cells." (PMID 33801272, 2021). "FBXL14 expression sensitized select cancer cells to the therapeutic activity of BMH-21 and led to the degradation of RPA194 in degradation-refractory cancer cell lines." (PMID 36372232, 2022). "We show that FBXL14 binds to RPA194 and mediates RPA194 ubiquitination and degradation in cancer cells treated with BMH-21." (PMID 36372232, 2022).
tumor (6 papers, 2019 to 2025). "These core genes—TRAF4, UBE2L3, FBXO45, UBE2L6, FBXL14, SKP2, CHAF1B, and WDR77—have been implicated in tumor progression in previous studies." (PMID 40990020, 2025). "Importantly, the expression of FBXL14 is abrogated in tumor tissues." (PMID 30999935, 2019).
FBXL14 also shares sentences with these, for which no sentence is quoted: autoimmune disorder (1 paper); cervical cancer (1); colon cancer (1); glioblastoma (1); hepatocellular carcinoma (1); lung carcinoma (1); osteosarcoma (1); ovarian carcinoma (1); pancreatic cancer (1).